MUC16 (mucin 16, cell surface associated)
Diseases named in the same sentence as MUC16 in open-access papers (continued):
Sharing a sentence is not in itself a finding about the gene and the disease.
lung adenocarcinoma (22 papers, 2014 to 2026). A carcinoma that arises from the lung and is characterized by the presence of malignant glandular epithelial cells. "Mucin 16 (MUC16) mutation ranks third among all common mutations in lung adenocarcinoma (LUAD), and it has a certain effect on LUAD development and prognostic outcome." (PMID 37341998, 2023). "For lung adenocarcinoma patients, MUC16 is found to be one of the most commonly mutated genes in predicted neo-antigens." (PMID 36357869, 2022). "Lung squamous cell carcinoma (LUSC) and lung adenocarcinoma (LUAD) share MUC16 and MUC17 mutations at a similar rate between the histological subtypes." (PMID 28978023, 2017). "On the other hand, USH2A, LRP1B, MUC16, and SYNE1 genes have been reported to have frequently mutated in various cancer types, particularly lung adenocarcinoma and lung squamous cell carcinoma." (PMID 30555633, 2018). "Our result suggested that mutations of TTN, MUC16 and CSMD3 may be associated with low expression of LINC02126 in lung adenocarcinoma." (PMID 36357869, 2022). "We examined MUC16 expression in pancreatic ductal adenocarcinoma (PDAC) and lung adenocarcinoma (LUAD) patients." (PMID 37567918, 2023). "FGF14 has been confirmed to inhibit tumor growth in lung adenocarcinoma, and this effect can be achieved by the inhibition of COL11A1 and MUC16 proteins by FGF14." (PMID 38040694, 2023). "Gene mutations observed differ between lung adenocarcinoma and lung squamous cell carcinoma, with KRAS, EGFR, LPHN3, KEAP1, and TLR4 being relatively common in lung adenocarcinoma, whereas BAI3, FBXW7, GRM8, ERBB4, MUC16, and RUNX1T1 are common in lung squamous cell carcinoma." (PMID 39594843, 2024).
prostate carcinoma (21 papers, 2013 to 2024). A carcinoma that arises from epithelial cells of the prostate gland. "This identified 60 glycopeptides as potential substrates for GCNT1 in prostate cancer cells, including a potential increase in core 2 O-glycan structures on PSAP and MUC16." (PMID 37813880, 2023). "Interestingly, T-C8 was found at the edge of the tumor slide, with high levels of MUC16 (a O-glycosylated protein of mucins) and PSCA (a prostate stem cell antigen and a specific marker of prostate cancer)." (PMID 37124494, 2023).
serous ovarian cancer (20 papers, 2008 to 2025). "Mucin 16 (MUC16) overexpression is linked with cancer progression, metastasis, and therapy resistance in high grade serous ovarian cancer and other malignancies." (PMID 38374055, 2024). "CA-125 is a large membrane glycoprotein encoded by the gene MUC16 that is overexpressed in 85% of serous ovarian cancers." (PMID 35454861, 2022). "Glycoprotein CA125A (cancer antigen 125, also known as mucin 16 [MUC16]), which is overexpressed in most serous ovarian cancers and is used as a diagnostic serum biomarker, was also assessed." (PMID 34965417, 2021). "The tumor-associated antigen CA125, encoded by the MUC16 gene, is detectable in the sera of most women with high-grade serous ovarian carcinomas (HGSOC)." (PMID 31039761, 2019). "For serous ovarian carcinomas a similar approach may also be possible to correlate specific O-glycan epitopes with the expression of MUC16/CA125 in order to improve the diagnostic value of this marker." (PMID 26075384, 2015). "The retained portion of MUC16/CA125 (MUC16ecto) represents a viable therapeutic target for high grade serous ovarian cancer and other solid tumor malignancies." (PMID 38374055, 2024). "The limited tissue expression of MUC16 has made it an attractive candidate for antibody-based, targeted therapy development in high grade serous ovarian cancer (HGSOC)." (PMID 38374055, 2024). "MUC16, encoding the CA125 antigen, circulates in the plasma of many patients with high-grade serous ovarian cancer." (PMID 25965947, 2015). "Gene copy number is one of several variables that will potentially alter the expression of MUC16 protein, but it is clear that MUC16 mRNA expression is often increased in serous ovarian cancer." (PMID 25965947, 2015). "Notably, a significant downregulation of miR-214-3p and miR-424-5p, which potentially regulate MMP7 and/or MUC16, was observed in the groups of serous ovarian carcinomas (LGSOC and HGSOC)." (PMID 37569592, 2023). "Furthermore, a significant increase in the expression levels of MMP7, MMP9, and MUC16 genes was observed in the serous ovarian carcinoma groups (LGSOC and HGSOC) when compared to the BSC group." (PMID 37569592, 2023). "In addition, for the majority of patients with serous ovarian cancer, the physical barrier and sink for therapeutic antibodies provided by soluble and membrane-bound MUC16, needs to be overcome." (PMID 32937961, 2020). "MUC16 is known to be expressed in most serous ovarian carcinomas and may function like MUC1 and MUC4 in tumor cell growth, motility and tumorogenicity." (PMID 26735499, 2016). "We hypothesized MUC16 is important in the serous ovarian cancer phenotype and suspected that expression of key elements from the MUC16 protein could promote invasive behavior in preclinical models of cancer, both in vitro and in vivo." (PMID 25965947, 2015). "Although intact MUC16 seems to be the dominant form on high grade serous ovarian cancer, our previous data suggest that a small fraction of cell surface MUC16 molecules may lack tandem repeat immunoreactivity but retain reactivity to MUC16ecto targeted antibodies like 4H11." (PMID 38374055, 2024). "MUC16 is one of the most well-known mucins, primarily because of its CA125 epitope, which serves as a biomarker for serous ovarian cancer." (PMID 37835533, 2023). "The expression of mucins (MUC16 and MUC1) and truncated O-glycans (Tn, STn and T) represents a characteristic footprint of serous ovarian carcinomas (SOCs)." (PMID 30011875, 2018). "We therefore intend to proceed with evaluation of MUC16, WFDC2, MSLN and MMP7, all of which have sensitivity >30% at 98% specificity in detection of clinically apparent serous cancers, beginning with analysis of serum specimens collected months to years prior to diagnosis of serous ovarian cancers." (PMID 18612378, 2008).
cervical cancer (19 papers, 2013 to 2025). A primary or metastatic malignant neoplasm involving the cervix. "In addition, we found significantly recurrent mutations in TTN (33%), MUC4 (31%), and MUC16 (19%), here reported for the first time, to our knowledge, in cervical carcinomas." (PMID 33664766, 2021). "MUC16 promoted growth and invasion of cervical cancer cells via JAK2/STAT3 phosphorylation-mediated COX-2 expression." (PMID 34150633, 2021). "Functional assays in cervical cancer cells revealed that overexpression of MUC16 activated the JAK2-STAT3 signal transducer pathway by STAT3 phosphorylation." (PMID 34150633, 2021). "Furthermore, it has been reported that MUC16 promotes proliferation and invasion via activation of the JAK2/STAT3 pathway in cervical cancer." (PMID 36199046, 2022). "The human cervical cancer cell line HeLa is an example of a native mix of MUC16-positive and negative cells." (PMID 27120790, 2016). "In contrast, non-targeted TR3 was incapable of shifting the MUC16 ratio in this cervical cancer cell line due to its non-targeted nature." (PMID 24447304, 2014). "In order to study target selectivity aspects of Meso-TR3 toward MUC16-expressing cancers, we took advantage of the fact that the cervical cancer cell line HeLa is comprised of a native mix of MUC16-positive and negative cells (80% and 20%, respectively)." (PMID 24447304, 2014). "Our results indicate that addition of mesothelin to the TR3 domain as in Meso-TR3, increases the effectiveness of TR3 in MUC16-positive malignancies such as ovarian and cervical cancers (shown for OVCAR3 and HeLa cell lines), while limiting its bioactivity on MUC16-negative Jurkat cells." (PMID 24447304, 2014).
colon cancer (19 papers, 2011 to 2025). "Additionally, we examined the co-occurrence of mutations in TSPs and colon cancer mutation-prone genes, and found that TSPs coexisted mutationally with MUC16, FAT4, OBSCN, and ZFHX4." (PMID 38827236, 2024). "Altogether, this suggests that MUC4/MUC16/MUC20high signature would be useful in stratification of patients with worst prognosis in several carcinoma and notably pancreatic, stomach and colon cancers." (PMID 30236127, 2018). "Although previous studies addressed the functional significance of various lengths of carboxyl-terminal MUC16 fragments (283 and 413 amino acids) in ovarian, breast and colon cancer cells, none demonstrated whether a cleaved MUC16 is generated following ectopic expression of these fragments." (PMID 25691062, 2015).
colorectal cancer (18 papers, 2009 to 2025). A primary or metastatic malignant neoplasm that affects the colon or rectum. "MUC16 stands out as one of the most frequently mutated genes in various cancers, with its overexpression linked to metastasis and tumourigenesis in ovarian, breast, pancreatic and colorectal cancers." (PMID 40478193, 2025). "However, MUC16 was still retained in the top 10 of mutated genes for lung and large intestine cancer after correcting for sequence length." (PMID 29552305, 2018). "Mutations of the APC, TTN, MUC16, and KRAS genes were high in frequency in both colorectal adenoma and colorectal cancer samples." (PMID 37546388, 2023). "In colorectal carcinoma, these rates are MUC1, 24–32%; MUC2, 38%; MUC3, 74%; MUC4, 94%; MUC5AC, 34–50%; MUC6, 39%; and MUC16, 64%." (PMID 25551773, 2014). "In appendiceal carcinoma, MUC3, MUC6 and MUC16 had lower expression, MUC2 expression was markedly higher, and MUC1 expression was higher than the respective rates in colorectal carcinoma." (PMID 25551773, 2014). "Whereas MUC5, MUC6, MUC16, and MUC20 are absent from the normal colon and are expressed in colorectal cancers." (PMID 36900282, 2023).
pancreatic ductal adenocarcinoma (18 papers, 2011 to 2025). An infiltrating adenocarcinoma that arises from the epithelial cells of the pancreas. "Elevated levels of Mucin-16 (MUC16) in conjunction with a high expression of truncated O-glycans is implicated in playing crucial roles in the malignancy of pancreatic ductal adenocarcinoma (PDAC)." (PMID 35628269, 2022). "In particular, the MUC16 gene has been shown to exert oncogenic effects in pancreatic ductal adenocarcinoma, with its aberrant expression enhancing the invasive phenotype of PDAC." (PMID 39546378, 2024). "The aim of our study was to evaluate the expression of Mucin 16 (MUC16) after neoadjuvant chemotherapy in pancreatic ductal adenocarcinoma tissue." (PMID 39456534, 2024). "MUC16 can promote the proliferation, invasion and migration of pancreatic ductal carcinoma in a variety of ways." (PMID 38758220, 2024). "Loss of MUC16 reduces the occurrence and metastasis of KRAS-induced pancreatic ductal adenocarcinoma by altering tumor microenvironmental factors." (PMID 38758220, 2024). "MUC16 was co-expressed and interacted with mesothelin proteins in both ovarian epithelial tumors and pancreatic ductal carcinoma, and the combination of the two promoted cancer metastasis and invasion." (PMID 38758220, 2024). "Recent studies have also found that MUC16 promotes the occurrence of hepatic metastasis of pancreatic ductal adenocarcinoma." (PMID 37670245, 2023). "Deletion of MUC16 decreases tumor cell migration in pancreatic ductal adenocarcinoma cells, which is in line with the decrease in proliferation and migratory ability in MUC16-silenced YTS-1 cells." (PMID 35864552, 2022). "A correlation has been shown between the upregulation of MUC16 and the progression of pancreatic ductal adenocarcinoma." (PMID 36051359, 2022). "Data from an immunohistochemistry analysis in 114 pancreatic ductal adenocarcinoma tissue samples show that MUC16 cytoplasmic expression elevates with increasing cancer stage, and is an independent predictor of poor prognosis." (PMID 29542355, 2018). "MUC16, a heavily glycosylated type-I transmembrane mucin is overexpressed in several cancers including pancreatic ductal adenocarcinoma (PDAC)." (PMID 27382435, 2016). "Having observed that MUC16 is aberrantly expressed in pancreatic ductal adenocarcinoma we next sought to study the expression of MUC16 during the development of PC." (PMID 22066010, 2011). "Further, in silico studies with The Cancer Genome Atlas (TCGA)-PAAD pancreatic ductal adenocarcinoma (PDAC) dataset revealed a positive correlation between MUC16 and 636 other genes (threshold set to exclude genes with median transcripts per million (TPM) < 0.5)." (PMID 35628269, 2022). "Additionally, in pancreatic ductal adenocarcinoma, MSLN attaching to CA125/MUC16 also stimulates MMP-7 manifestation via the p38 MAPK pathway." (PMID 40227616, 2025). "Long-term survivors of pancreatic ductal adenocarcinoma (PDAC) are enriched in MUC16/CA125 neoantigens, suggesting that MUC16 may serve as a candidate immunogenic hotspot in PDAC." (PMID 34207556, 2021).
glioma (17 papers, 2019 to 2025). A benign or malignant brain and spinal cord tumor that arises from glial cells (astrocytes, oligodendrocytes, ependymal cells). "We have identified a high frequency of MUC16 mutations in patients with non‐in situ relapsed glioma and have begun anti‐PD‐1/PD‐L1 therapy trials in these patients." (PMID 40022576, 2025). "The SHOX2high group (n = 175) showed high frequency of somatic mutations in the EGFR (40%), PTEN (36%), TTN (36%) and MUC16 (26%) genes in glioma." (PMID 37170390, 2023). "Importantly, although immune infiltration varied in G34 glioma patients, patient 1 in our cohort who harbored MUC16 mutation had obviously high immune infiltration and achieved the longest OS of 75 months." (PMID 35109850, 2022). "In addition, frequently observed mutations to EGFR (27%), IDH1 (20%), PTEN (18%), and MUC16 (16%) were present in gliomas with low TOX expression (n = 158)." (PMID 32762688, 2020). "In particular, MUC16, also known as CA-125, merits additional investigation given its emergence as a distinctive grading feature, since current literature supports this marker in ovarian cancer with clinical use; however, it is identified as mutated in only a relatively small percentage of gliomas." (PMID 37760597, 2023). "We found that different recurrence patterns of gliomas had different driver mutations, and genetic alterations of some genes were enriched in different gliomas, among which MUC16 was enriched in patients with non‐in situ recurrence." (PMID 40022576, 2025). "Specific mucins that have now been implicated in glioma include MUC1, MUC4, MUC15, MUC16, MUC17, MUC18 and MUC21." (PMID 39767713, 2024). "The frequency of mutations for PIK3CA, MUC16 and TTN was significantly higher in high risk glioma cases (TTN, 26% vs. 7%; MUC16, 16% vs. 8%; PIK3CA, 10% vs. 3%)." (PMID 33946049, 2021). "MUC16 is involved in cell migration and is implicated in mutations present in post-TMZ treated gliomas." (PMID 33216820, 2020). "Few mutations were identified in MUC16 in primary GBM samples, but a 15 percent mutation frequency was observed in recurrent GBM in the CGGA (Chinese Glioma Genome Atlas) GBM database, validating our results." (PMID 31822636, 2019). "The mutation frequencies of IDH1 and ATRX in gliomas with a low-risk score were remarkably higher than in gliomas with a high-risk score (IDH1, 92% vs. 31%; ATRX, 33% vs. 21%), while TTN and MUC16 had lower mutation frequencies (TTN, 8% vs. 21%; MUC16, 7% vs. 10%)." (PMID 36311792, 2022). "Based on the current literature, expression profiles, and biological properties, MUC1, MUC4, MUC16, and MUC18 are of interest as precision biomarkers in glioma." (PMID 39767713, 2024). "Moreover, the EGFR and MUC16 mutations were also significantly enriched in cases within high‐risk group, while mutations in CIC, NOTCH1, ATRX, and CDH12 occurred more frequently in the low‐risk group, these characteristics are consistent with the update WHO CNS5 classification of glioma." (PMID 35985661, 2022).
hepatocellular carcinoma (17 papers, 2016 to 2023). A malignant tumor that arises from hepatocytes. "Encoding cancer antigen 125 (CA125), MUC16 is frequently mutated and highly related to the prognosis in various tumors, including cholangiocarcinoma, ovarian carcinoma, hepatocellular carcinoma, and GC." (PMID 36744128, 2023). "Little is known about the association between cancer antigen 125 (MUC16/CA125) concentrations and tumor diameter of patients with hepatocellular carcinoma (HCC) and low AFP levels." (PMID 31662990, 2019). "MUC16 and TTN, which are mutated in 11.1% and 20.2% of human hepatocellular carcinomas, were not captured by exome sequencing." (PMID 35557512, 2022).